VWF (von Willebrand factor)
Diseases named in the same sentence as VWF in open-access papers (continued):
Sharing a sentence is not in itself a finding about the gene and the disease.
thrombotic disease (40 papers, 2012 to 2026). The formation of a blood clot in the lumen of a vessel or heart chamber; causes include coagulation disorders and vascular endothelial injury. "In the context of high plasma VWF levels and thrombotic disorders, silencing of one VWF allele will lower VWF in the circulation and endothelial cells, but at the same time, allele-selective silencing prevents an excessive reduction in VWF levels." (PMID 41743270, 2026). "Circulating nucleic acids (CNAs), high-mobility group box 1 (HMGB1), von Willebrand factor (vWF), and S100b protein are notable markers of SI, indicative of tissue damage and implicated in thrombotic disorders." (PMID 41311551, 2025). "VWF and some hemostatic and fibrinolytic components are independent risk factors for thrombotic disease." (PMID 36944974, 2023). "Non‐O blood type (BT) is a risk factor for thromboses, which has been attributed to its effects on von Willebrand factor (VWF)/factor VIII (FVIII) levels." (PMID 32052552, 2020). "Growing evidence suggests that inflammation is strongly associated with thrombosis through VWF‐mediated reactivity, which interacts with tissue factor‐initiated fibrin formation and may lead to extensive thrombotic disease." (PMID 37435773, 2023). "High plasma levels of VWF correlated with an increased risk of thrombotic diseases." (PMID 32231163, 2020). "Prospective studies are needed to assess whether the association of oxidative stress and VWF abnormalities is only a sustained epiphenomenon of thrombotic diseases or is causally related to macroangiopathic complications in diabetic patients." (PMID 23383177, 2013). "VWF plays a crucial role in supporting hemostasis, which is important in bleeding as well as thrombotic disorders." (PMID 41743270, 2026). "This SI is driven by factors like circulating nucleic acids (CNAs), S100b, high-mobility group box 1 (HMGB1), and von Willebrand factor (vWF), which reflect tissue damage and contribute to thrombotic disorders, including the formation of blood clots." (PMID 41311551, 2025). "VWF is a macromolecular plasma protein that plays a key role in maintaining normal coagulation and contributes to thrombotic disorders following endothelial and platelet dysfunction." (PMID 41188339, 2025). "Although TMA and SOS/VOD are not the same disease, in that TMA is caused by vascular endothelial cell injury, it is interesting to observe similar VWF multimer behavior in the 2 thrombotic diseases after HSCT." (PMID 39247211, 2024). "Novel VWF and GP inhibitors are in various phases of development and upcoming clinical trials should clarify their role in the management of thrombotic diseases involving platelet activation." (PMID 35328719, 2022). "As VWF is critical to primary hemostasis and also a number of thrombotic diseases, its level, size, and binding activity are tightly regulated." (PMID 33883551, 2021). "Understanding the mechano-activation mechanism of VWF is key to elucidate the pathophysiology of thrombotic diseases and to develop safe anti-thrombotic therapeutics." (PMID 33883551, 2021). "Some researchers suggest that vitamin B12 might facilitate or even trigger abnormal VWF deposition in thrombotic disorders." (PMID 40625905, 2025). "Activated platelets may occasionally contribute to the circulating pool of VWF in patients with thrombotic disorders, but platelet VWF after release from α granules tends to remain bound to the platelet surface." (PMID 24034700, 2013). "Lower clearance of vWF in non-O individuals and the association between higher vWF-levels and thromboses may explain the association between the TC allele of rs8176719 and postoperative VTE." (PMID 34777790, 2021). "In particular, disease-specific upregulation of SERPINE1 (encoding plasminogen activator inhibitor-1; PAI-1), VWF (von Willebrand factor), and GZMB (Granzyme B) gene expression levels in COVID19 + ICU patients may contribute to thrombotic disorders in COVID19 patients." (PMID 33306162, 2020).
thrombotic disease (continued). "The interaction of platelet GPIbα with VWF through their respective LBD and A1 domains is critical to thrombus formation in many thrombotic diseases." (PMID 33883551, 2021). "The ADAMTS13 protease regulates vWF activity by cleaving vWF multimers; therefore, an imbalance between vWF and ADAMTS13 may contribute to the development of thrombotic disorders." (PMID 41516301, 2025). "In particular, VWF levels may be a plausible mediator of the association of non-O blood groups with CHD and other thrombotic disorders." (PMID 23408959, 2013).
malaria (39 papers, 2009 to 2025). Malaria is a serious and sometimes fatal disease caused by a parasite that commonly infects a certain type of mosquito which feeds on humans. "This systematic review and meta-analysis indicate that vWF levels are significantly elevated in individuals with Plasmodium infections, suggesting a possible association with malaria pathophysiology." (PMID 40283058, 2025). "Concerning mortality, vWF levels were linked to mortality and gradually decreased over time in survivors of severe malaria." (PMID 40283058, 2025). "This systematic review and meta-analysis aimed to consolidate data on vWF levels in malaria and evaluate their association with disease severity." (PMID 40283058, 2025). "The subgroup analysis showed significant differences in the SMDs of vWF levels associated with Plasmodium infections based on geographic location, age ranges, Plasmodium species, and diagnostic methods for malaria and vWF." (PMID 40283058, 2025). "Association with disease severity and vWF, this was found in malaria patients co-infected with HIV and in malaria patients only, respectively." (PMID 34663245, 2021). "While little is known about the role of VWF self-association in malaria, both VWF and platelets likely play an important pathophysiological role in SM, functioning to facilitate the attachment of infected erythrocytes and directly occluding the vessel." (PMID 26830467, 2016). "Recently, endothelial activation markers such as ang-2, soluble Tie-2 receptor, vWF have been shown to be associated with severe malaria." (PMID 24674301, 2014). "WPB-associated proteins Ang-2, vWF, and vWF propeptide were elevated in children with severe malaria compared to UM, as were inflammatory biomarkers CRP, PCT, and sTREM-1 (p<0.01)." (PMID 21364762, 2011). "This elevation of vWF could serve as a key biomarker of endothelial activation, reflecting the inflammatory and coagulation disturbances caused by malaria." (PMID 40283058, 2025). "Several studies have suggested that vWF levels are elevated in malaria; however, the nature of this association, particularly concerning disease severity, remains unclear." (PMID 40283058, 2025). "Further prospective and well-controlled studies are essential to clarify its diagnostic and prognostic value and to determine whether vWF can meaningfully contribute to clinical decision-making in malaria management." (PMID 40283058, 2025). "Additionally, vWF is upregulated in malaria infection and have been associated with malaria severity caused by Plasmodium falciparum." (PMID 31935960, 2020). "The similar levels of VWF and propeptide in both categories suggest that VWF levels are not able to discriminate between cerebral malaria and coma due to other causes in the presence of malaria parasites." (PMID 22125593, 2011). "Additionally, geographical differences in study populations over time may contribute, as variations in malaria transmission intensity, endemicity, and host immune responses can affect disease presentation and associated biomarkers such as vWF." (PMID 40283058, 2025). "Moreover, elevated vWF may be linked to the decrease in platelet count, which was notably reduced in malaria patients, especially those with severe malaria." (PMID 40283058, 2025). "While some reports indicate a significant increase in vWF levels in infected individuals, the extent to which vWF contributes to malaria pathophysiology or serves as a biomarker for disease severity has not been systematically assessed." (PMID 40283058, 2025). "Despite these limitations, the study highlights the need for further investigation into the role of vWF in malaria pathogenesis." (PMID 40283058, 2025). "Conclusions: vWF levels are significantly elevated in individuals with Plasmodium infections, indicating a potential role in malaria pathophysiology." (PMID 40283058, 2025).
malaria (continued). "Following the removal of 442 duplicates, 1205 records were screened, and 956 were excluded due to irrelevance to the study topic (malaria and von Willebrand factor)." (PMID 40283058, 2025). "In analyses comparing severe and less severe malaria, vWF levels are significantly elevated in severe P. falciparum cases, suggesting a potential role of vWF in disease severity." (PMID 40283058, 2025). "In patients with malaria and HIV co-infection, vWF levels were more profoundly elevated compared to those with either condition alone, and levels were significantly increased in both malaria and HIV patients compared to those with only one of these infections." (PMID 40283058, 2025). "Marked upregulations of the vWF and ANG-2 have also been found in oedematous alveoli in post-mortem lung sections of Thai patients with malaria-associated ARDS (MA-ARDS)." (PMID 37375081, 2023). "The plasma concentrations of the biomarkers for endothelial activation, such as the von Willebrand factor (vWF) and angiopoietin-2 (ANG-2), are markedly elevated in severe malaria and have been associated with both the severity and mortality of the illness." (PMID 37375081, 2023). "When released, vWF induces platelet recruitment to the surface of the endothelial cells to foster the cytoadherence of malaria-infected red blood cells to the endothelium." (PMID 31935960, 2020). "In line with previous findings, cytoadherence linked proteins VWF and ADAMTS13 were identified to vary in plasma abundance between malaria-infected and uninfected individuals." (PMID 30442134, 2018). "In malaria, however, ADAMTS13 activity is reduced and VWF can persist and self-associate into large multimers which can bind platelets." (PMID 26830467, 2016). "The combined increases in plasma levels of both VWF and OPG observed in severe malaria are of further interest in that previous studies have demonstrated that OPG can bind directly to the A1 domain of VWF." (PMID 26766771, 2016). "In severe malaria patients, also reduced levels of von Willebrand factor (vWF) cleaving protease, ADAMTS13, and increased vWF levels have been found." (PMID 26743539, 2016). "Elevated VWF levels have been reported in children with asymptomatic parasitaemia, suggesting that malaria parasites induce a state of endothelial activation even at early stages of infection." (PMID 26830467, 2016). "More recently, the role of ADAMTS13 (a von Willebrand factor (VWF) cleaving protease) activity has also been discussed to explain malaria-related microangiopathy." (PMID 24812562, 2014). "Beside sequestration of IE, severe malaria is characterised by systemic endothelial activation and widespread release of activation markers such as von Willebrand factor (vWF), soluble ICAM-1(sICAM-1) and angiopoietin-2 (ang-2)." (PMID 24674301, 2014). "In a prospective study of patients from Ghana with different malaria presentations, we showed that patients with severe P. falciparum infection had significantly increased plasma VWF and propeptide levels, consistent with acute endothelial cell activation." (PMID 22125593, 2011). "In the current prospective study we investigated plasma VWF and propeptide levels in paediatric malaria." (PMID 22125593, 2011). "Our findings show that VWF and propeptide levels are markedly elevated in patients with retinopathy positive cerebral malaria but less so in mild malaria." (PMID 22125593, 2011). "In summary, we have confirmed that plasma VWF and propeptide levels are markedly elevated in both cerebral and mild paediatric malaria, discriminate between these two conditions and that in cerebral malaria these normalize upon recovery." (PMID 22125593, 2011). "We, and others, have reported that levels of Ang-2 and vWF, and the ratio of serum/plasma Ang-2 to Ang-1 are quantitative and independent biomarkers of malaria severity and outcome." (PMID 22110737, 2011).
malaria (continued). "We have previously shown evidence of endothelial activation in Ghanaian children with malaria, indicated by elevated plasma levels of both von Willebrand factor (VWF) and its propeptide." (PMID 22125593, 2011). "As well as enabling IE to sequester in vascular beds which do not express appropriate IE receptors, this novel mechanism also provides a link between the observed high levels of VWF in malaria and platelet-mediated IE adhesion to brain endothelium." (PMID 22125593, 2011). "In children with malaria plasma VWF and propeptide levels are markedly elevated in both cerebral and mild paediatric malaria, with levels matching disease severity, and these normalize upon recovery." (PMID 22125593, 2011). "Further work on the specificity and sensitivity of VWF and VWF propeptide is therefore required to ascertain their role as prognostic biomarkers for malaria disease severity." (PMID 22125593, 2011). "Recent reports have described increased circulating concentrations of VWF and activation of the coagulation system in severe malaria, with possible implications for pathogenesis." (PMID 21209923, 2010). "Severe malaria has been associated with increased levels of VWF and ULVWF multimers and decreased levels of the regulatory VWF-specific cleaving protease ADAMTS13 (A disintegrin and metalloprotease with thrombospondin type-1 repeats)." (PMID 21209923, 2010). "Since vWF is involved in both hemostasis and inflammation, its elevated levels in malaria may reflect the connection between the immune response and coagulation pathways during infection." (PMID 40283058, 2025). "Interestingly, a von Willebrand factor was upregulated in 'amakihi experimentally infected with malaria that died from infection, hinting at potential antagonistic pleiotropy between adaptation to high elevations and susceptibility to infection." (PMID 40909016, 2025). "A comprehensive search across six databases identified studies reporting vWF levels in malaria." (PMID 40283058, 2025). "Background and Objectives: Elevated von Willebrand factor (vWF) levels have been reported in malaria, but their relationship with disease severity remains unclear." (PMID 40283058, 2025). "This suggests that vWF could play a key role in the thrombotic and hemorrhagic manifestations often seen in severe malaria cases." (PMID 40283058, 2025). "Additionally, the observed rise in vWF levels during Plasmodium infections has significant implications for understanding the pathophysiology of malaria-related complications." (PMID 40283058, 2025). "Moreover, vWF levels were significantly increased in both uncomplicated malaria and asymptomatic Plasmodium infections compared to children without parasitemia." (PMID 40283058, 2025). "By providing a clearer understanding of vWF alterations in malaria, this study may help inform clinical management strategies, improve early detection of hemostatic imbalances, and guide future research on the prognostic value of vWF in malaria outcomes." (PMID 40283058, 2025). "It has been hypothesized that the VWF may be involved in the pathogenesis of this parasitic malaria, but the mechanisms behind it are still being investigated." (PMID 38745860, 2024). "(ii) In the malaria group as a whole, both IL-18 and IL-18bp were positively correlated with disease severity, parasitemia, and endothelial cell activation as assessed by vWF in plasma." (PMID 34663245, 2021). "Furthermore, plasma VWF:Ag and VWFpp levels have also been shown to correlate with other biochemical prognostic markers in patients with severe malaria." (PMID 26766771, 2016). "Nevertheless, emerging data suggest that the early release of WP body contents, and in particular VWF, may play a role in malaria pathogenesis." (PMID 26766771, 2016). "Further studies will be required to determine whether increased levels of this VWF-OPG complex are circulating in patients with severe malaria." (PMID 26766771, 2016).